FOXP3 (forkhead box P3)
Diseases named in the same sentence as FOXP3 in open-access papers (continued):
Sharing a sentence is not in itself a finding about the gene and the disease.
tumor (continued). "Surprisingly, researchers found significantly more FoxP3+ Tregs in low-grade tumours from female patients compared with tumours from male patients." (PMID 36928373, 2023). "The results showed that LFA-1 was highly correlated with Foxp3 in SKCM, and the LFA-1 expression level is negatively associated with tumor cells purity and positively associated with the infiltration of CD4 + T cells and CD8 + T cells." (PMID 37723552, 2023). "They identified increases in FoxP3 + regulatory T cells and a reduction in Th1 cells in a dose-dependent manner, which they subsequently confirmed in a mouse subcutaneous tumour xenograft model." (PMID 37798728, 2023). "Simultaneously, the proliferation or activation of FOXP3+ Tregs under IM severely inhibits tumor immunity." (PMID 37753092, 2023). "Inhibition of Foxp3 leads to a rise in expression and activity of PPARγ, as well as lowering the expression of NF-κB and Cyclin D1, which inhibit tumor growth and migration and promote cell apoptosis." (PMID 37345200, 2023). "Regarding the tumor microenvironment in EC, it is known that regulatory T cells and their marker FOXP3 are correlated with worse survival rates." (PMID 36068443, 2023). "It is worth mentioning that CD4+FoxP3+ Tregs surrounding S15+ tumor cells had the most significant prognostic values (P = 0.008)." (PMID 37674198, 2023). "We also observed a proportion of CD4+ TILs with a FoxP3+T-bet+ phenotype that increased during tumour outgrowth." (PMID 37153625, 2023). "Mechanistically, LINC00853 promoted PDZK1IP1 expression through binding to FOXP3, thus maintaining tumor stemness and accelerating tumor progression." (PMID 37403034, 2023). "FOXP3+ T regulatory cell (Treg) enrichment has also been observed in glioblastoma and other high-grade tumor types." (PMID 36768342, 2023). "The IHC results demonstrated that the FoxP3 in tumor cell protein expression was higher in tumors than in their adjacent normal kidney tissues, and a higher expression level of FoxP3 protein in tumor cells was related to higher TNM stages." (PMID 37569676, 2023). "Foxp3, being the master transcription factor of Treg cells, is epigenetically regulated and is responsible for a stable Treg cell population in tumor-bearing mice and humans." (PMID 36672677, 2023). "On the other hand, other authors have described low FOXP3 infiltrate as being a predictor of favorable tumor prognosis." (PMID 36765559, 2023). "It is also now well established that Foxp3+ Treg cells have a significant role in several types of cancers, and targeting them has been shown to significantly enhance anti-tumor immune responses." (PMID 35802166, 2023). "For instance, the depletion of αSMA+ myofibroblasts in PDAC suppressed tumor immune surveillance with an increase in the percentage of regulator T cells (Treg, CD4+Foxp3+), which led to aggressive tumor progression and reduced animal survival." (PMID 37784082, 2023). "The BTC tumor edge serves as the primary location for active infiltration by FOXP3+CD4+ Tregs that express elevated levels of lymphocyte activation gene 3 (LAG-3) and T cell immunoglobulin and mucin domain-containing protein 3 (TIM3)." (PMID 38213535, 2023). "In order to evaluate the change of tumor microenvironment response to psychological stress, we conducted a multiplex immunofluorescence staining including CD11b, Ly6G, FOXP3, CD8, and CD206." (PMID 37210553, 2023). "The α-Enolase (ENO1) specific Th17 cells have specific anticancer effects in PAAD patients, and compared with healthy mucosa, the abundance of Th17 in peripheral blood of tumor patients is low, while the proportion of FOXP3+Tregs is high." (PMID 37396042, 2023). "Summarily, S15+ tumor cells or TAMs were spatially closer to CD4+FoxP3+ Tregs, and S15+ tumor cells were positively correlated with the spatial density of TAMs, and spatially closer to TAMs." (PMID 37674198, 2023).
tumor (continued). "Depletion of TRAMs before tumor engraftment can lead to lower tumor burden, reduced FOXP3+ Tregs, and increased IFN-γ+ CD8 T cells, indicating TRAMs support the early stage of NSCLC development." (PMID 37822933, 2023). "It has been determined that FoxP3+ Tregs have the capacity to facilitate the development of an immunosuppressive milieu within biliary tumors, hence augmenting tumor cell proliferation, invasion, and metastasis, ultimately leading to an unfavorable prognosis." (PMID 38115302, 2023). "In BO patients, highly replicating Ki-67+ tumor cells, low tumor HLA-I expression and abundant FoxP3+ lymphocytes were found (p=0.037; p=0.056 and p=0.021)." (PMID 37691949, 2023). "Although there is consensus regarding the tumor-suppressing role of Foxp3 in the normal mammary gland, its role in the pathogenesis of BRCA remains controversial." (PMID 37766222, 2023). "In the same model, when treated with cyclophosphamide-loaded PD-1 presenting platelets, Tregs (FoxP3+) decreased at the tumor site and tumor infiltrating CD8+ T cells significantly increased." (PMID 37106400, 2023). "When DKK1 was overexpressed in this tumour model the proportion of FOXP3‐positive Treg was increased from an average of 5.3% (n = 64) in the vector control group up to 10.7% (n = 19) of cells (p < .001)." (PMID 35924447, 2023). "A Foxp3–GARP–TGF-β axis was proposed to represent an important signaling pathway in the primary tumor microenvironment for different types of cancer." (PMID 38067325, 2023). "This leads to autophagy in the cancer cells with a noticeable shift in the tumor microenvironment, with a decrease in the detrimental FOXP3+ regulatory T cells and a subsequently beneficial increase in CD8+ cytotoxic T lymphocytes." (PMID 37999101, 2023). "In patient P03, the distribution pattern of spatial T cells switched after nAde, recruited tumor-reactive T cells such as PD-1+ CD8+ T cells and suppressive FOXP3+ CD4+ Treg cells were distributed in the tumor margin and rarely infiltrated into tumors." (PMID 37488287, 2023). "We identified Nrp-1 to facilitate the migration of CD4+Foxp3+ Tregs into tumor tissues in response to VEGF." (PMID 38019895, 2023). "In the CAC model, the transient depletion of Foxp3+ Treg cells during tumor progression results in suppressed tumor growth and dissemination." (PMID 38288125, 2023). "Studies from 2012 until 2022 report great discrepancy in the prognostic value of FoxP3+ TILs within variable tumour types." (PMID 36564565, 2023). "It uses multiplexed immunofluorescence for the simultaneous visualization and quantification of CD68 + macrophages, CD8 + T cells, FOXP3 + regulatory T cells, PD-L1/PD-1 protein expression, and tumor cells." (PMID 36959234, 2023). "Significantly elevated CD3+CD8+Foxp3- cytotoxic T cells were detected in tumor samples from glioma patients after RT." (PMID 37833255, 2023). "The population of T cells was also regulated upon rivaroxaban treatment, reducing the immune-suppressive regulatory CD4+ FoxP3+ T cells and increasing tumor-killing granzyme B+ CD8 T cells." (PMID 37444590, 2023). "Densities and percentages of CD8+ T cells, CD4+ T cells, FoxP3+ T cells, CD20+ B cells, M1 and M2 tumor-associated macrophages and NK cells (CD56dim and CD56bright) were quantified." (PMID 36969032, 2023). "The combination treatment of peptide R and anti-PD-1 reduced the infiltration of forkhead box P3 (FoxP3) positive cells (a major marker of Treg cells), tumor growth, anti-PD-1 sensitivity and tumor drug resistance." (PMID 37497001, 2023). "For instance, tumor-associated macrophages (TAMs) and CD4(+) CD25(+) Foxp3(+) regulatory T cells (Tregs) are associated with poor prognosis in patients with HCC." (PMID 37133437, 2023). "Accompanying these changes in the composition of CD4+ TILs, the proportion of CD4+ FoxP3+T-bet+ cells increased during tumour outgrowth." (PMID 37153625, 2023).
tumor (continued). "Metastasis was preceded by low CD8+T cell/FoxP3+Treg ratios, creating pre-metastatic niches in the tumor-draining lymphatic basin." (PMID 36905477, 2023). "This was recently shown to be due to losartan enhancing CD8+ T-cell infiltration and decreasing Tregs in the TME and reducing immunosuppressive FoxP3+ cancer cells, thus enhancing anti-tumor immunity and tumor cell killing." (PMID 37520562, 2023). "We suggest that exclusion of CD4+FOXP3+ cells is a tumour-permissive requirement mandatory for the maintenance of tumour-driving chronic antigenic stimulation and LP : Tfh cell interactions." (PMID 37854674, 2023). "In conclusion, we found that propolis, a natural supplement, potentially prevented CRC progression by increasing CD3+ and CD4+ TILs and reducing FOXP3 lymphocytes in the tumor microenvironment of early stage CRC." (PMID 37960147, 2023). "Studies has shown that the hypoxia inside the tumor microenvironment can promote FoxP3 expression or impact the cytokine profile inside to attract Tregs." (PMID 37051250, 2023). "Our data showed that FOXP3+ expression was frequently observed in tumor and peri-tumoral compartments, suggesting that regulatory CD4+ lymphocytes had a greater tendency to infiltrate tumoral parenchyma." (PMID 37366900, 2023). "FOXP3‐expressing Treg cells, which suppress aberrant immune response against self‐antigens, also can suppress anti‐tumor immune response." (PMID 36650632, 2023). "According to the results of our single-cell transcriptomic analysis and flow cytometry of tumor-infiltrating immune cells, OV-mOX40L treatment decreased Foxp3+ Tregs, activated CD4+ and CD8+ T cells, and resulted in less exhausted CTLs." (PMID 37554264, 2023). "Compared to patients with progressive disease (PD), progression-free (PF) subjects show a brisker stromal immune infiltrate, higher proximity of tumor-infiltrating CD3+ T cells to PD-L1+ tumor cells and of FOXP3+ T cells to proliferating CD11c+ myeloid cells." (PMID 37349318, 2023). "Togashi’s study showed that Treg cells expressing FOXP3 suppress aberrant immune responses against autoantigens and also suppress anti-tumor immune responses." (PMID 36860325, 2023). "FoxP3 is a specific biomarker of Tregs that can infiltrate into the microenvironment of many tumor types, and it is related to poor prognosis for cancer patients." (PMID 37569676, 2023). "Infiltration of cells with low-intensity FOXP3 expression was significantly higher in MCPyV-positive MCC cases than in MCPyV-negative MCC cases in the central tumor area (p = 0.004)." (PMID 37573372, 2023). "The tumor suppressor Lkb1 is known to regulate the expression of forkhead box P3 (Foxp3), thereby maintaining the levels of Foxp3+ regulatory T cells (Treg) that play a crucial role in self‐tolerance." (PMID 36515008, 2023). "A worse prognosis has been documented for SCLC patients with tumor infiltrates that contain larger proportion of FOXP3+ cells." (PMID 37206058, 2023). "For example, tumor-specific sympathetic denervation downregulated the expression of programmed death-1 (PD-1), PD-L1 and FOXP3, suppressing tumor progression." (PMID 37834436, 2023). "Myeloid-ILK deficiency also enhances tumour-infiltration of CD8+ T cells and reduces FOXP3+ T cells in CAC and APCmin/+-driven CRC, respectively, with a significantly elevated CD8+/FOXP3+ ratio indicating a tumoricidal impact in both models." (PMID 38077324, 2023). "TIM-3+Foxp3+ Treg cells express IL-10 and upregulate CTLA-4 and PD-1 expression, and these cells display more tumor suppressive function than TIM-3–Foxp3+ Treg cells." (PMID 36810098, 2023). "In contrast, the number of FOXP3-positive cells was significantly higher in the invasive front than in the tumor center in MCPyV-negative cases, for both low- (p < 0.0001) and high-intensity (p = 0.0021) FOXP3-expressing cells." (PMID 37573372, 2023).
tumor (continued). "And for the FOXP3 + regulatory T cells, it demonstrating a significantly decreased infiltrating diversity in the tumour of mice treated with LCAR-M23 CAR T cells." (PMID 36166071, 2023). "Despite high heterogeneity among the articles regarding treatment received, type of tumor reported, and techniques used to evaluate immune infiltrate, we found a significant decrease of TILs and FoxP3 expression after neoadjuvant chemotherapy." (PMID 37104271, 2023). "We found that a higher number of Foxp3+ T cells and higher Foxp3/CD4 and Foxp3/CD8 ratios at the invasive front of the tumor were associated with LN metastasis." (PMID 37958412, 2023). "Cell-depleting anti-CCR4 mAb therapy is instrumental for evoking and enhancing tumor immunity in humans via selectively removing effector-type FOXP3+ Treg cells." (PMID 36839882, 2023). "The changes in (a) CD8, PD-1, PD-L1, TGF-β1 and FOXP3 levels in the tumor nodules and (b) serum levels of IL-2, IL-10 and TGF-β1 in the MTE-treated mice were similar to those in the AOM/DSS mice, as seen by immunohistochemistry." (PMID 37649480, 2023). "inducing an exodus of α4β7+ Th17 and RORγt+ FoxP3+ regulatory (Tr17) CD4+ T cells towards the tumor." (PMID 37999101, 2023). "CD8- and FOXP3-positive cell infiltrations were higher in the invasive front than in the tumor center." (PMID 37573372, 2023). "Among the T cells, both the CD4+ and CD8+ subpopulations were ~10-fold larger, while the percentage of CD4+Foxp3+ T regulatory (Treg) cells, which are negative regulators of antitumour immunity, was much smaller in tumours from TIOs+NIR3-treated mice." (PMID 37673934, 2023). "FOXP3+ TILs suppress tumor-promoting inflammatory responses under the presence of the enteric bacteria." (PMID 36693070, 2023). "The results demonstrated that tumours with high cytoplasmic S100A2 were enriched for infiltration of CD3+FOXP3+ cells (positive, P < 0.001) and CD163+ cells (positive, P = 0.009)." (PMID 37476187, 2023). "An inhibitory VISTA antibody reduced the emergence of tumor-specific Foxp3+CD4+ Tregs, and suppressed tumor growth in melanoma." (PMID 37190254, 2023). "Here, we intended to further evaluate the effects of Foxp3 on the characteristics that facilitate tumor progression, such as chemoresistance and migration, in human and murine experimental BRCA." (PMID 37766222, 2023). "It was reported to be expressed at high levels in tumor-infiltrating Foxp3+ Tregs in several types of murine cancers." (PMID 36839882, 2023). "The number of CD8+ T lymphocytes and the release of proinflammatory IFN-γ was increased significantly, while the accumulation of Foxp3+ Treg cells within the tumor was reduced." (PMID 36428632, 2022). "We found that aPD1/ADA gel increased CD8+ T cells and IFNɣ in tumors and decreased CD4+FoxP3+ regulatory T cells (Tregs) in tumor draining lymph nodes." (PMID 36132332, 2022). "Cancer‐associated fibroblasts in the extracellular matrix express COX‐2, which promotes PGE2 secretion to induce immunosuppressive FOXP3+ Tregs, which then accumulate in primary tumour tissues and the peripheral blood to promote immune evasion." (PMID 34877770, 2022). "Mechanistically, VISTA expression on APCs and tumor cells hampers effective T-cell tumor reactions by reducing T-cell proliferation and cytokine production, as well as inducing the activation of Foxp3+ Tregs." (PMID 36499220, 2022). "It has been shown that a high frequency of tumor-infiltrating FoxP3+ Tregs predicts improved survival in mismatch repair-proficient CRC patients." (PMID 35655158, 2022). "In vitro studies have shown that the expression level of FOXP3 increases with the enhancement of the metastatic potential of tumor cell lines." (PMID 36235242, 2022). "In CRC, a local immune response and tumour-infiltrating FOXP3+ T-regulatory cells inversely correlated with a systemic inflammatory response, which associated with a poor prognosis in various cancers." (PMID 35328734, 2022).
tumor (continued). "We observed lower densities of FOXP3+ TAICs in the tumor compartment of nCRT‐treated patients compared with non‐nCRT‐treated resections." (PMID 34743329, 2022). "PDPN-positive CAF cases display high CD204+ tumor-associated macrophage (TAM) levels and a low CD8/FOXP3 T cell ratio." (PMID 35159384, 2022). "Infiltration of FOXP3-positive cells in various cancers has been reported to correlate with tumor stage and poor prognosis." (PMID 36132149, 2022). "Numerous investigations have revealed that immunosuppressive regulation of Foxp3+ Treg cells is an essential mechanism of tumor immune escape." (PMID 35402261, 2022). "This study observed that Ki67+-proliferating CD8+ T cells and FOXP3+ Tregs were increased in tumor samples four weeks following irradiation." (PMID 35055015, 2022). "We found that higher levels of tumour-infiltrating T cell subsets, including CD8+PD-1+LAG-3+TIM-3+, CD4+FoxP3+CTLA-4+ T and CD68+STING+ cells, were associated with inferior overall survival (OS) in 80 patients." (PMID 35982052, 2022). "In two cases of tumor tissue collected before and after treatment, we confirmed that mogamulizumab reduced the number of Foxp3+ and CCR4+ cells." (PMID 35131860, 2022). "There is also an elevated expression of FOXP3 in tumor-infiltrating Treg cells which correlates with up-regulation of COX-2 and its product PGE2." (PMID 35563052, 2022). "Among tumor-infiltrating Tregs, investigators detected T-bet+Foxp3+CD4+ T cells with a higher expression of typical Treg factors, such as ICOS, GITR, CD103, CTLA4, PD-1, and IL-10 as compared to CD4+ T cells, which express either T-bet or Foxp3." (PMID 35626725, 2022). "But the ratio of Foxp3+Treg cells to CD8+T cells also increased markedly in the high-risk score group (P=0.029), suggesting a more immunosuppressive tumor microenvironment with increased Treg cell infiltration." (PMID 36081499, 2022). "Flow cytometric staining of CD45.2-enriched tumor-derived cells further revealed that depletion of tumor-infiltrating CD4+CD25+Foxp3+ Tregs was accompanied by a more general and severe depletion of tumor-infiltrating CD4+ T cells." (PMID 35972798, 2022). "CRC patients with high levels of tumor-infiltrating FoxP3+ Tregs had a higher chance of survival, in contrast to those with other types of solid tumors." (PMID 36146549, 2022). "Conversely, the specific ablation of RORγt in Foxp3+ Treg cells of polyp-prone mice improves anti-tumor responses and reduces polyposis." (PMID 35874729, 2022). "The utility of CD8+ tumor-infiltrating lymphocytes (TILs) or FOXP3+ TILs as independent prognostic factors in NSCLC patients is controversial." (PMID 35222387, 2022). "Conversely, CD4+ T-helper 2 and FoxP3+ regulatory T cells seem to contribute to tumor immune escape." (PMID 36010653, 2022). "Both FoxP3+ cells (TILs and BC cells) and MDSCs seem to have prognostic significance in BC and other tumor entities." (PMID 35158964, 2022). "Previous studies have shown that IDO1 and 2 can suppress anti-tumor immune response by activating CD4+CD25+Foxp3+ regulatory T cells (Treg) and myeloid-derived suppressor cells (MDSCs), which consequently inactivate CTLs." (PMID 35656514, 2022). "To examine the corresponding impact of ACT+MS-275 treatment on Treg abundance, we stained frozen tumor sections with anti-Foxp3 antibody for immunohistochemistry and immunofluorescence imaging." (PMID 35972798, 2022). "Previous studies have already suggested that FoxP3 expression accurately defines the population of TGFβ expressing Tregs that accumulate in tumor sites where antitumor immunity is evident." (PMID 36551693, 2022). "Nuclear FoxP3 was expressed exclusively by stroma infiltrating lymphocytes, which migrated between the tumor cells in some cases." (PMID 36098901, 2022). "Second, the relative abundance of CD4+Foxp3+ Tregs at the tumor site was substantiallylower in mice that received the NIE-NPs treatment than that in micetreated with CNIE-NPs, i.e., 4.97% vs 13.0%." (PMID 35926215, 2022).